INS (insulin)
Diseases named in the same sentence as INS in open-access papers (continued):
Sharing a sentence is not in itself a finding about the gene and the disease.
glucose metabolism disorders (127 papers, 2013 to 2026). "Aging-related glucose metabolism disorder is a progressive, multi-organ, and multifactorial condition caused by reduced skeletal muscle insulin sensitivity, adipose tissue redistribution and inflammation, and gradual decline in β-cell secretory capacity." (PMID 41357171, 2025). "On the other hand, β-cell dysfunction with insufficient insulin secretion is another leading cause of Tac-induced glucose metabolism disorder." (PMID 40495121, 2025). "Gravidas with a higher degree of glucose metabolism disorders requiring insulin therapy have a higher risk of developing other complications during pregnancy." (PMID 39796611, 2025). "TPX, derived from the mangiferin derivative 1,3,6,7-tetraallylloxy ketone, can restore the insulin signaling pathway, increase liver glycogen synthesis, and protect against IR caused by glucose metabolism disorders in liver cells." (PMID 40290429, 2025). "It plays a role in regulating estrogen levels and, to some extent, is involved in insulin metabolism as it can aggravate glucose metabolism disorders and cause indirect functional damage to the central nervous system." (PMID 39554652, 2024). "Accordingly, HTP exhibits a more pronounced impact on ameliorating glucose metabolism disorders and enhancing insulin sensitivity compared to LTP, thereby mitigating the risk factors associated with NAFLD." (PMID 37628072, 2023). "At the cellular level, IR primarily manifests as glucose metabolism disorder caused by insulin stimulation to target cells or tissues, especially skeletal muscle tissue." (PMID 33623531, 2021). "Our findings identify BAFF as a therapeutic target to improve insulin sensitivity with potential applications in the prevention and treatment of aging-associated glucose metabolic disorders." (PMID 32698539, 2020). "Palmitate is among these TAG molecular species and is known to cause glucose metabolic disorder by the impairment of insulin signaling in skeletal muscle cells and adipocytes." (PMID 29875018, 2018). "In patients with β-T major a progressive damage of insulin-producing cells due to secondary hemosiderosis appears to be the most reasonable mechanism associated with glucose metabolism disorders." (PMID 27123460, 2016). "While accumulated Aβ causes glucose metabolic disorder by disturbing the insulin signaling pathway, altered glucose metabolism can conversely promote Aβ accumulation." (PMID 27763550, 2016). "The enhancement of the phosphatidylinositol metabolism in diarrhea rabbits may be caused by glucose metabolism disorder, and insulin is activated by plasma membrane measurement near phosphatidylinositol 3-kinases (PI3Ks)." (PMID 36139297, 2022). "In addition, as glucose metabolism disorders cause chronic microvascular lesions, insulin secretion can directly or indirectly affect the progression of DKD." (PMID 36466094, 2022). "Additionally, GALP enhances insulin sensitivity in adipose tissue and skeletal muscle, and its downregulation may contribute to glucose metabolism disorders, thereby increasing GDM susceptibility." (PMID 40458174, 2025). "Serum glucose concentrations, as well as serum TG and serum INS concentrations, have become the basic indicators of glucose metabolism disorders since their abnormal elevation is caused by the impaired function of glucose utilization for cells induced by glucose metabolism disorders." (PMID 39457933, 2024). "Blocking the RAAS system holds promise for improving insulin sensitivity and β-cell function, and potentially reversing abnormal glucose tolerance or ameliorating glucose metabolism disorders." (PMID 40106408, 2025). "Our prior research demonstrated that dietary intake of high-oxidative pork (HOP) induced by HTP cooking impairs pancreatic insulin secretion and induces glucose metabolism disorders in mice." (PMID 41008194, 2025).
glucose metabolism disorders (continued). "Inflammatory cytokines stimulate an increase in insulin secretion, and excess insulin secretion further impairs pancreatic islet function, leading to glucose metabolism disorders." (PMID 40084146, 2025). "This method involves exposing zebrafish to high-concentration glucose solutions, creating a hyperglycemic environment that places stress on the pancreas, leading to insulin resistance and glucose metabolism disorders." (PMID 40458823, 2025). "ameliorates insulin sensitivity and glucose metabolism disorders by regulating the IRS1/PI3K/AKT signaling pathway and the expressions of its downstream targets GLUT4, FOXO1, and GSK3β." (PMID 40351361, 2025). "At the transcriptional level, HM018 significantly improves insulin sensitivity and alleviates glucose metabolism disorders." (PMID 40535017, 2025). "Brain insulin resistance weakens the response of brain neurons to insulin, resulting in brain glucose metabolism disorder, which plays an important role in the pathogenesis of AD." (PMID 40316481, 2025). "Prior studies reported a 2–5-fold higher risk of glucose metabolism disorders in PCOS, suggesting a shared pathophysiologic background in insulin action and secretion." (PMID 41384021, 2025). "In terms of glucose metabolism disorders, blood glucose-related indicators (HbA1c, fasting insulin levels) play an important role." (PMID 38310324, 2024). "In the spontaneous T2DM with NAFLD model of this study, the mice showed glucose metabolism disorder-related manifestations such as abnormal blood glucose, lipid, and insulin levels." (PMID 39054547, 2024). "This reduction weakens bile acid metabolism, resulting in glucose metabolism disorders, decreased insulin sensitivity, and significant fluctuations in blood glucose levels." (PMID 39109082, 2024). "Lipid intermediates made with free fatty acids and lipid droplet leads to down -regulates insulin signaling pathways and glucose metabolic disorders." (PMID 39283905, 2024). "In the mouse IR model, the mice showed glucose metabolism disorder related phenotypes such as elevated blood glucose, serum insulin, GSP and abnormal glucose tolerance." (PMID 37822878, 2023). "Our experiments in mice also showed the TAC-induced glucose metabolic disorders were dose dependent, such as fasting glucose level and fasting insulin level." (PMID 37151651, 2023). "Inhibiting MCP-1 signaling can partially restore the proliferation and insulin secretion of islet cells, ultimately ameliorating glucose metabolism disorder." (PMID 37957155, 2023). "The upregulated MCP-1, in turn, worsens glucose metabolism disorder by inhibiting the proliferation and insulin secretion of islet cells through an endocrine pathway." (PMID 37957155, 2023). "As a key regulator of glucose metabolism disorders, insulin promoted DNA damage, ROS and Ca2+ homoeostasis imbalance in a panel of established EC cell lines." (PMID 36526973, 2022). "Body weight, fasting glucose, glucose tolerance test (GTT), and insulin tolerance test (ITT) were used to evaluate glucose metabolism disorder." (PMID 36299624, 2022). "Previous studies showed GQD ameliorates glucose metabolism disorders, and increases the sensitivity of the tissues to insulin in type 2 diabetic and HFD-induced IR rats." (PMID 35067163, 2022). "Bacteroidetes is reported to improve glucose metabolism disorders and restore insulin sensitivity and profit maintaining the integrity of the intestinal barrier." (PMID 36406423, 2022). "Insulin resistance (IR), the core defect of T2DM, is a pathological state involving the inability of receptors to react efficiently in response to insulin stimulation, resulting in an intracellular glucose metabolism disorder." (PMID 35842638, 2022). "SIVmac239 infection induced obvious glucose metabolism disorder, as seen by the decrease in insulin and c-peptide in plasma and increase in glucose." (PMID 34630335, 2021).
glucose metabolism disorders (continued). "Justification of insulin employment in TTS is supported by studies using 18F-FDG uptake confirming the presence of glucose metabolism disorder, similar to that observed in stunned or hibernated myocardium, for which insulin has been proposed." (PMID 34362223, 2021). "Suppression of glucose uptake by TMEM16A also generates secondary effects by enhancing gluconeogenesis and glucose metabolic disorder, thereby exacerbating insulin resistance, lipogenic events, inflammatory responses, and other NAFLD‐related events." (PMID 32440483, 2020). "Peripheral insulin administration efficiently attenuated liver dysfunction and glucose metabolic disorders by suppressing hypothalamic anorexigenic neuropeptide proopiomelanocortin (POMC) expression, hepatic NF‐κB pathway and STAT3 phosphorylation." (PMID 29285858, 2018). "Earlier in vivo studies demonstrated that tanshinone IIA improves glucose tolerance, insulin sensitivity and glucose metabolic disorders via increasing AMPK activity." (PMID 24739942, 2014). "STZ not only destructs the part function of islet beta cells so that glucose metabolism disorders, but also induces insulin resistance, which results in the increase of insulin level in blood." (PMID 25177729, 2014). "Key mechanisms primarily involve oxidative stress and cellular apoptosis, while telomere dysfunction may also contribute to glucose metabolism disorders by impairing pancreatic β-cell function and peripheral tissue insulin sensitivity." (PMID 41872659, 2026). "Therefore, abnormal insulin signal transduction in PD patients can also lead to cerebral glucose metabolism disorders." (PMID 39962629, 2025). "PD may lead to glucose metabolism disorders through mechanisms such as intestinal microbial disorders, autonomic nerve dysfunction, abnormal insulin signal transduction and decreases of dopamine receptors." (PMID 39962629, 2025). "This research initially demonstrated the multi-targeted approach of polysaccharide degradation by Noni juice, which can replicate the combined effects of “Nrf2 activators and GSK3β inhibitors” to enhance insulin sensitivity and mitigate glucose metabolism disorders." (PMID 40941105, 2025). "And high starch could cause insufficient secretion of INS and ADPN and then induce glucose metabolic disorders and abnormal glycogen accumulation." (PMID 38668364, 2024). "Our observation of the increase in serum glucose, TG, and INS concentrations in broilers when exposed to light for an extended duration provides compelling evidence supporting the idea that long photoperiods can lead to glucose metabolism disorders." (PMID 39457933, 2024). "Similarly, Mg2+ deficiency is involved in impaired glucose metabolism since it blocks the insulin pathway, reduces kinase dependence, and induces an acute-phase response related to a decrease in insulin sensitivity and subsequent glucose metabolism disorder." (PMID 39202546, 2024). "Compared with naïve C57BL/6J mice, SELENOF KO mice showed the differential expression of hepatic proteins involved in the glucose metabolic pathways, glucose intolerance and insulin reduction, suggesting that glucose metabolism disorders were induced by SELENOF KO." (PMID 36358477, 2022). "Honokiol ameliorated glucose metabolism disorder by increasing glucose consumption, insulin-stimulated 2-NBDG uptake, and translocation of GLUT2 and alleviated oxidative stress by reducing ROS accumulation and loss of mitochondrial membrane potential in glucosamine-induced HepG2 cells." (PMID 36466390, 2022). "In the current study, glucose metabolism disorder, including increased glucose concentration and decreased insulin and c-peptide levels, was detected in the NPMs following long-term SIVmac239 infection, similar to antiretroviral-naïve patients with HIV infection." (PMID 34630335, 2021). "Tangminling was showed to improve insulin sensitivity, which might be another potential mechanism to regulate glucose metabolic disorder." (PMID 30948503, 2019).
glucose metabolism disorders (continued). "Furthermore, glucose metabolism disorders during pregnancy may also be exacerbated by low vitamin D levels due to its role in insulin sensitivity." (PMID 41001383, 2025). "In addition, combined cART, metformin, and insulin treatment may be suitable for long-term infectors with glucose metabolism disorder to limit spermatogenic dysfunction." (PMID 34630335, 2021). "Furthermore, previous studies found that HFD also causes glucose metabolism disorder and insulin insensitivity, which are important driving factors in the occurrence of NAFLD and NASH, whereas FFDZ intervention markedly enhanced insulin sensitivity and glucose tolerance." (PMID 40144651, 2025). "Glucose metabolic disorder is a typical symptom of patients with OSA and usually occurs with an increase in glucose and insulin resistance." (PMID 27480913, 2016). "microRNA-450a-5p could inactivate the insulin signal pathway by targeting the inhibited Dual Specificity Phosphatase 10 (DUSP10) and inducing IR and glucose metabolism disorders in vitro cultured hepatocytes and adipocytes." (PMID 39912972, 2025). "Alternatively, HDL-C and Apo A-I (the main protein component of HDL-C) inhibit cytokine- or glucose-induced apoptosis in β-cells and promote insulin secretion by means of the S1P signaling pathway, and the reduction in HDL-C in patients with NAFLD further promotes glucose metabolism disorders." (PMID 39280011, 2024). "The changed levels of glucose, insulin, and c-peptide in the SIV+ NPMs implied that pancreatic islet β cell dysfunction may be the starting point of glucose metabolism disorder during SIVmac239 infection." (PMID 34630335, 2021). "Compared with the NC group, the fasting blood glucose, insulin, HOMA-IR and AUC of OGTT levels in the HFD group were significantly increased (p < 0.05), indicating that NAFLD mice featured the characteristics of glucose metabolism disorder." (PMID 35052765, 2021). "However, TMI was not significantly correlated with FBG, HbA1c, OGTT 2-hour blood glucose level, or OGTT 2-hour blood insulin levels in patients with glucose metabolism disorder or those without." (PMID 38457571, 2024). "Thus, glucose metabolism disorder occurs when the islet B cells do not compensate for the increased insulin secretion." (PMID 29292753, 2017). "Finally, because insulin signals independently of RAS-PI3Kα interaction, drugs that break this interaction are unlikely to induce glucose metabolism disorders." (PMID 41272322, 2026). "Consequently, the absence of additional markers, including fasting glucose, insulin, and HOMA index, represents a limitation in the precise characterization of glucose metabolism disorders." (PMID 40453587, 2025).
Cirrhosis (126 papers, 2008 to 2026). A chronic disorder of the liver in which liver tissue becomes scarred and is partially replaced by regenerative nodules and fibrotic tissue resulting in loss of liver function. "This association may reflect the unique metabolic profile of cirrhosis, characterized by impaired insulin sensitivity and altered glucose utilization." (PMID 41575963, 2026). "Patients with cirrhosis may be associated with beta cell dysfunction and decreased insulin secretion." (PMID 35252271, 2022). "In patients, FMT has been shown to: improve insulin sensitivity in patients with metabolic syndrome, improve cognitive function in patients with cirrhosis and HE; and restore antibiotic-associated disruption in microbial diversity and function in patients with advanced cirrhosis." (PMID 34066064, 2021). "For the patient with NASH, the associated weight gain with insulin creates a management conundrum; this is especially true for patients with cirrhosis who are given tight glycaemic control and weight loss targets to qualify for listing for transplant at many centres." (PMID 33102791, 2020). "Thus, a detailed analysis of the association of ALR deficiency, changes in insulin levels, iron overload and fibrosis/cirrhosis with GLRX5 and hepcidin reduction in the presence of underlying liver injury warrants future investigation." (PMID 26808690, 2016). "Other agents, such as sulfonylureas and alpha-glucosidase inhibitors, are generally avoided in decompensated cirrhosis, and insulin therapy, though often used, requires further evidence to support its efficacy." (PMID 41529239, 2026). "For treating T2DM, glucagon-like peptide-1 receptor agonists and coagonists, sodium-glucose cotransporter-2 inhibitors, metformin (if glomerular filtration rate exceeds 30 mL/min), and insulin (in decompensated cirrhosis) are preferred." (PMID 41752724, 2026). "Comparative studies between GLP-1RAs and other antidiabetic agents, such as insulin, metformin, and sulfonylureas, show that GLP-1RAs are associated with reduced risks of hepatic decompensation, cirrhosis, HCC, and all-cause mortality." (PMID 41607999, 2026). "Limited clinical evidence is also available regarding the safety and efficacy of antidiabetic medications in individuals with cirrhosis, with insulin therapy remaining the safest option for such patients." (PMID 40004572, 2025). "Despite these limitations, insulin often remains the preferred glycemic controlled agent for patients with decompensated cirrhosis and T2DM." (PMID 40444235, 2025). "Exercise has been shown to improve insulin sensitivity and slow the progression of cirrhosis by facilitating the process of glucose uptake and metabolism and reducing insulin resistance." (PMID 38996156, 2024). "MASLD is regarded as a multifaceted pathological process encompassing aberrant lipid metabolism, insulin resistance, inflammation, gut microbiota imbalance, apoptosis, fibrosis, and cirrhosis." (PMID 39440040, 2024). "Although baseline insulin concentrations were highest in cirrhosis, patients with NAFLD showed the greatest postprandial increase in insulin." (PMID 37078380, 2023). "DPP-4 inhibitors users exhibited a significantly reduced risk of HCC (aHRs: 0.53, 95% CIs: 0.44–0.65) after adjustment for age, sex, chronic hepatitis C virus infection, cirrhosis, anti-virus drug use, and insulin use." (PMID 36831491, 2023). "Sixty-two percent were men and alcoholics, ranging from 54 (±14) to 58 (±9) years old; 16.6% were diabetics who used insulin (21.4%); and all had cirrhosis." (PMID 35674591, 2022). "Studies have shown that patients with severe HBV infection and cirrhosis can have increased insulin resistance, and some patients can have abnormal glucose metabolism." (PMID 35899024, 2022). "In our group of cirrhotic liver transplant candidates, leptin levels correlated with IR, BMI, and insulin concentrations, indicating several possible mechanisms of hyperleptinemia in the context of cirrhosis." (PMID 32092909, 2020).